DNMT3B (DNA methyltransferase 3 beta)
Diseases named in the same sentence as DNMT3B in open-access papers (continued):
Sharing a sentence is not in itself a finding about the gene and the disease.
colorectal cancer (continued). "The exploration of DNMT3B inhibitors and their efficacy in mitigating colorectal cancer progression further signifies the translational implications of this research." (PMID 39108206, 2024). "In summary, their findings provide evidence suggesting that miR-124 exerts suppressive effects on the proliferation, and invasion of colorectal cancer cells via DNMT3B downregulation." (PMID 37705098, 2023). "Overexpression of DNA-methyltransferases, including DNMT3B, at both the mRNA and protein level has been described for several malignancies, including prostate, lung, breast, and colorectal cancer; glioblastoma; and leukemia." (PMID 36361596, 2022). "To confirm the localisation of DNMT3B in colorectal cancer cells, we then assayed the localisation of ectopically expressed T7-DNMT3B in RKO cells using ChIP-qPCR." (PMID 33514701, 2021). "Taken together, these experiments confirm that the CGIs marked by H3K36me3 are those which are most strongly targeted by DNMT3B in colorectal cancer cells." (PMID 33514701, 2021). "Taken together these experiments suggest that DNMT3B activity is highest at CGIs that are marked by H3K36me3 in colorectal cancer." (PMID 33514701, 2021). "In colorectal carcinoma, knockout of both DNMT1 and DNMT3B caused promoter demethylation of TIMP3, thus increasing the TIMP3 mRNA level." (PMID 31624299, 2019). "One study has shown that HOXB13 as a direct DNMT3B target is aberrantly methylated at an upstream CpG island, and functions’ tumor suppressor properties in colorectal cancer cells." (PMID 30105866, 2018). "Recently, DNMT3B has emerged as one of causes of CpG island methylation in tumor; nonetheless, the association between DNMT3B and CIMP in colorectal cancer is at most modest and tumor CpG island methylation appears to be influenced by additional factors." (PMID 21738611, 2011). "PLCG2 is identified as a key downstream regulatory protein of DNMT3B in colorectal cancer." (PMID 39108206, 2024). "Overall, our results suggest that de novo DNMT activity is primarily targeted to H3K36me3 marked CGIs irrespective of the DNMT responsible but support a model in which the bulk of the de novo DNMT activity at H3K36me3 marked CGIs is dependent of DNMT3B in colorectal cancer cells." (PMID 33514701, 2021). "Based on previous studies that suggested DNMT3B expression might contribute to the CpG island methylator phenotype in colorectal cancer, we investigated DNMT3B as a DNA demethylase conformer member." (PMID 33042830, 2020). "Studies have shown that DNMT3B can induce DNA methylation in specific CpG islands in colorectal cancer and it could also induce the distinct methylation level in different regions such as CpG and non-CpG." (PMID 31828117, 2019). "Furthermore, it was shown that the DNMT3B -149C>T polymorphism was linked to altered methylation levels of cancer related genes, such as hMLH1 and ECAD, in colorectal cancer cells." (PMID 31370354, 2019). "To do this, we first used a well-established model, the paired colorectal cancer lines HCT116 and its derivative HCT116 DKO (double knockout), which carries mutations in two of the methyltransferase genes DNMT1 and DNMT3B and is known to be hypomethylated at many loci." (PMID 30777123, 2019). "Furthermore, DNMT3B expression increases during colorectal cancer progression and correlates positively with the methylation level of CIMP marker genes." (PMID 22563479, 2012). "The relative distribution of -149C>T DNMT3B SNPs among a Chinese population can not be used as a stratification marker to predict an individual's susceptibility to colorectal cancer." (PMID 18662374, 2008). "However, the relative distribution of -149C>T DNMT3B SNP among a Chinese population can not be used as a stratification marker to predict an individual's susceptibility to colorectal cancer." (PMID 18662374, 2008).
colorectal cancer (continued). "As a first approach to meDNA-guided alternative splicing and its possible impact on cancer, we examined HCT116 human colorectal cancer cells with the DNA methylases DNMT1 and DNMT3b inactivated." (PMID 34086943, 2021). "DNMT3B possesses 'de novo' activity that establishes DNA methylation pattern, and it has been shown to be induced by PGE2 in colorectal cancer." (PMID 31534549, 2019). "To further confirm the functional impact of DNA methylation alterations on gene expression, we utilized two human colorectal carcinoma cell lines, namely HCT116 wild type and HCT116 DNMT1/DNMT3B double knockout (DKO) cells." (PMID 30911103, 2019). "miR-23b together with a number of miRs were found to be overexpressed in human colorectal carcinoma HCT116 double DNMT1 and DNMT3b knockout (DK) cells as compared to the HCT116 parental cells." (PMID 28077801, 2017). "Both Dnmt1 and Dnmt3b interact with the polycomb group repression complexes (PRC1 and PRC2), and regulate distinct sites in colorectal cancer development." (PMID 26808831, 2016). "To observe the consequences of PADI4-mediated DNMT3A upregulation specifically, we used the colorectal cancer cell line HCT-116, where both the DNMT1 and DNMT3B DNMTs have been genetically disrupted (DKO cells) and where DNMT activity is minimal." (PMID 24957603, 2014). "Since our data indicated a strong link between DNA methylation and the H3K36me3 mark, we investigated epigenetic profiles in the HCT116 colorectal cancer cell line and in its isogenic counterpart with double knockout of DNMT1 and DNMT3B." (PMID 21526191, 2011). "We next analyzed methylation of each gene in a colorectal cancer cell line (HCT116) after partial knockout of DNMT1, knockout of DNMT3b or knockout of both enzymes (DKO)." (PMID 17967063, 2007). "This is consistent with what is observed in human colorectal carcinoma cells, which appear to require both DNMT1 and DNMT3b expression to retain p16 silencing via promoter region hypermethylation." (PMID 17938735, 2007). "In addition, at the post-translational modification level, the RNA-binding protein HuR has been demonstrated to regulate DNMT3B by binding to its 3’-UTR and increasing its protein levels in colorectal cancer cells." (PMID 40595027, 2025). "Of note, PGE2, which is the most abundant prostanoid in colorectal cancer, promotes anti-tumor immune responses by inducing Treg and MDSCs and promotes tumor initiation and growth by upregulating the expression of DNMT1 and DNMT3B." (PMID 38607004, 2024). "Moreover, low miR-203 expression in colorectal cancer leads to ABCG2 promoter methylation and significantly reduced expression by attenuating the inhibition of DNMT3B, which was consistent with our results." (PMID 37421455, 2023). "Consistent with this, in HCT116 colorectal cancer cells lacking DNA methyltransferases DNMT1 or DNMT3B, LCT13 expression decreases, while cells lacking both DNMTs or treated with the DNMT inhibitor 5-azacytidine (5-aza) show no change in LCT13 expression." (PMID 28300471, 2017). "In addition, colorectal carcinoma (CRC) cells which were subjected to hypoxia and hypoglycemia had reduced DNMT1, DNMT3a, and DNMT3b mRNAs, resulting in a decrease in the 5mC level at the proximal promoter region of p16INK4a." (PMID 26861406, 2016). "Additionally, we comprehensively characterized the DNA methylation profiles of a colorectal carcinoma cell line pair (HCT116 and DKO, which was generated through double knock-out of DNMT1 and DNMT3b in HCT116)." (PMID 23324053, 2013). "DNMT3B -579G>T genotypes and -149C>T were determined by PCR-RFLP and sequencing in 137 colorectal cancer patients and 308 controls matched for age and sex, who did not receive radiotherapy or chemotherapy for newly diagnosed and histopathologically confirmed colorectal cancer." (PMID 18662374, 2008).
colorectal cancer (continued). "To do this, we initially used the well-characterised pair of colorectal cancer cell lines HCT116 wild type (WT) and double knockout (DKO), which have high methylation levels at most loci in WT and low levels in the daughter cell line DKO due to decreased levels of DNMT1 and DNMT3B enzymes." (PMID 35578268, 2022). "Furthermore, different genes are hypermethylated in cancers such as CDKN2A, hMLH1, and APC in colorectal cancer (CRC); p16INKa, RB1, and VHL1 in renal cell carcinoma; TET2, DNMT3B, IDH1, BRAF, and MYC in prostate cancer; and MGMT in colon, lung, lymphoid, and other tumors." (PMID 35327559, 2022). "In colorectal cancer and melanoma, BACH1 heterodimerizes with MAF BZIP Transcription Factor G (MAFG), cooperating with chromodomain helicase DNA-binding protein 8 (CHD8) and DNA Methyltransferase 3 Beta (DNMT3B) to inhibit the transcription of many antioncogenes." (PMID 35651942, 2022). "Part of the de novo DNMT activity we measure at H3K36me3 marked CGIs in colorectal cancer cells could therefore be mediated by DNMT3A rather than DNMT3B but is primarily dependent on DNMT3B for recruitment." (PMID 33514701, 2021). "OPCML-v1 could also be induced in the colorectal cancer cell line HCT116 which is completely methylated for this gene, by genetic demethylation through double knock-out of both DNA methyltransferases DNMT1 and DNMT3B (DKO cell line)." (PMID 18714356, 2008). "We also found that SOX10 could be activated in the colorectal cancer cell line HCT116 which is completely methylated for this gene, by genetic demethylation through only double knockout (KO) of both DNMT1 and DNMT3B (DKO cell line), but not single KO of DNMT1 or DNMT3B alone (1KO or 3BKO cell line)." (PMID 25301735, 2014).
colon carcinoma (55 papers, 2008 to 2025). "30UTR DNMT3B is a HuR protein target in human colon cancer cells, caused by DNA hypermethylation of their target genes." (PMID 37107631, 2023). "One of the best-studied systems in humans consists of HCT116 colon cancer cells carrying a hypomorphic allele in the DNMT1 gene together with a DNMT3B knockout (HCT116 DKO cells)." (PMID 29598829, 2018). "In this study, we used Infinium methylation arrays to interrogate the methylation level of putative DNMT3B target genes in DNMT3B-overexpressing and in DNMT3B-deficient colon cancer cells." (PMID 22563479, 2012). "Since both DNMT1 and DNMT3a are unable to compensate for DNMT3b loss, it is plausible that colon carcinoma cells contain an unidentified component of the DNA methylation pathway which is absent in PC3 cells." (PMID 18798999, 2008). "DNMT3b deficiency in colon cancer cells results in a very nominal 3% reduction in DNA methylation levels and does not appear to alter the methylation status of any genes." (PMID 18798999, 2008). "The present result, and those from lung and colon cancer which are the only published data on association between DNMT3B SNP and cancer development, can show the different possible roles of DNMT3B in different cell types." (PMID 18662374, 2008). "Carriers with the G allele in the DNMT3B gene were found to have a decreased risk of colon cancer compared with individuals with the T allele." (PMID 18662374, 2008). "DNMT3B activity has been linked with aberrant methylation of CpG islands in colon cancer." (PMID 30555653, 2018). "Previous studies have shown that pSTAT3 activation enhances DNMT3B expression in hepatocellular carcinoma and colon cancer." (PMID 40427627, 2025). "Two studies have shown that DNMT3B overexpression and CIMP-high expression are closely associated with colon tumors." (PMID 38542774, 2024). "To study DNMT3B splicing in partially differentiated cells, we chose HCT116 cells, a colon cancer stem–like cell line, where DNMT3B was shown to be expressed, active, and to play a role in DNA de novo methylation and maintenance." (PMID 38809976, 2024). "To better delineate the downstream regulatory proteins of DNMT3B in CRC, we treated HCT1116 colon cancer cells with the DNMT3B inhibitor SGI-1027 (SGI) for 24 h, collected the cells, and performed transcriptomic sequencing." (PMID 39108206, 2024). "The results indicated that VIRMA and DNMT3B had higher mRNA expression levels in colon cancer tissue, which was consistent with the protein level results." (PMID 37421455, 2023). "Preclinical studies demonstrated that overexpression of DNMT3B promotes primary tumour progression in melanoma and colon cancer." (PMID 37592220, 2023). "For example, important elevations of DNMT3B and DNMT1 expression have been associated with tumorigenesis, particularly in colon cancer (CC)." (PMID 37107631, 2023). "The results indicated that VIRMA and DNMT3B were significantly higher in colon cancer tissue, which was consistent with the previous analysis." (PMID 37421455, 2023). "Next, we further explored the mRNA expression levels of VIRMA and DNMT3B in 10 pairs of colon cancer and normal tissues with RT-qPCR." (PMID 37421455, 2023). "Similar to our findings, a previous study reported rDNA destabilization upon genetic ablation of DNMT1 and DNMT3b in human colon cancer cells." (PMID 33081395, 2020). "Although single knockout of either Dnmt1 or Dnmt3b gene had minimal effects on DNA demethylation in colon cancer cells, 19 knockouts of both Dnmt1 and Dnmt3b genes led to demethylation and re‐expression of tumor suppressor genes in these cells." (PMID 31090214, 2019). "(E) Comparison of global DNA methylation changes that occur in human colon cancer and in mouse intestine when Dnmt3b is overexpressed." (PMID 30468428, 2018). "Overexpression of DNMT3B has been shown to induce DNA methylation in specific genes promoter and colon tumor formation in mice." (PMID 30555653, 2018).
colon carcinoma (continued). "DNMT1 and DNMT3B double‐knockout HCT116 colon cancer cells showed that let‐7a‐3 methylation is cooperatively maintained by the DNA methyltransferases DNMT1 and DNMT3B just like other genomic regions." (PMID 27097729, 2016). "Annurca apple polyphenol extracts inhibited the expression of DNMT1 and DNMT3b in colon cancer cells." (PMID 24822169, 2014). "Black Raspberry-derived anthocyanins were first shown to inhibit DNMT1 and DNMT3B in colon cancer cells." (PMID 24822169, 2014). "Altogether, our data show no general association between a high protein expression level of DNMT3B and hypermethylation of CIMP markers in different colon cancer cell lines." (PMID 22563479, 2012). "Our results confirm that depletion of DNMT3B specifically reduced the proliferation rate of DNMT3B-overexpressing colon cancer cell lines." (PMID 22563479, 2012). "As previous studies have implicated DNMT3B in colon cancer development, we subsequently focused on characterizing the role of DNMT3B in colon cancer cell lines." (PMID 22563479, 2012). "To further analyze the role of DNMT3B in DNA methylation in colon cancer, we analyzed the effects of DNMT3B knockdown on the genomic DNA methylation pattern." (PMID 22563479, 2012). "Using quantitative real-time PCR and immunoblotting, we screened a panel of human colon cancer cell lines for DNMT3B expression on the mRNA and protein level." (PMID 22563479, 2012). "Based on our model, a dual specific DNMT1 and DNMT3B inhibitor would be the most efficient approach to reverse the hypermethylation phenotype in colon cancer cells." (PMID 22563479, 2012). "While our results show that DNMT3B knockdown impacts on the proliferation of colon cancer cells, they also demonstrate that the enzyme is dispensable for the hypermethylation phenotype in these cells." (PMID 22563479, 2012). "DNMT3B mRNA expression was elevated in lung, breast, cervix, ovarian, liver, gastric and colon cancers, respectively." (PMID 22563479, 2012). "In summary, our results demonstrate that high levels of DNMT3B are required for the proliferation of a subset of colon cancer cell lines, which is consistent with a proposed oncogenic function of the protein." (PMID 22563479, 2012). "By demonstrating that silencing of DNMT3b in prostate derived cells has a more dramatic effect than its absence in colon carcinoma cells, this work also supports the notion that other yet unidentified factors are likely to influence DNMT3b activity." (PMID 18798999, 2008). "In addition, DNMT3B depletion in DNMT3B-overexpressing colon cancer cell lines induced apoptosis and inhibited proliferation." (PMID 38368287, 2024). "Finally, we validated m6A/m5C/m1A regulators at the protein and mRNA expression levels, which further identified that VIRMA and DNMT3B played vital roles in colon cancer." (PMID 37421455, 2023). "Recently, black raspberry-derived anthocyanins, a subclass of flavonoids, have been demonstrated to suppress the enzymatic activities and protein levels of DNMT1 and DNMT3B in multiple colon cancer cell lines, including HCT116, Caco-2, and SW480 cells leading to demethylation." (PMID 37111085, 2023). "Finally, we validated that the mRNA and protein expression of VIRMA and DNMT3B increased in colon cancer tissues." (PMID 37421455, 2023). "Furthermore, the expression of DNMT1 and DNMT3b were all elevated in human colon cancer tissues as compared to the adjacent normal colon tissues." (PMID 34268315, 2021). "Heterogeneous degrees of DNMT1 overexpression are associated with primary colon cancer cells, while DNMT3B overexpression has been related to CIMP-high colon cancer, although the overexpression of the protein not always parallels the RNA levels." (PMID 32806509, 2020). "We further examined the biological function of DNMT3B in colon cancer." (PMID 31815008, 2019). "Furthermore, knockdown of DNMT3B enhanced the radiosensitivity of colon cancer HCT116 cells to both γ-irradiation and carbon-ion beam irradiation." (PMID 26667181, 2015).